ACE (angiotensin I converting enzyme)
Diseases named in the same sentence as ACE in open-access papers (continued):
Sharing a sentence is not in itself a finding about the gene and the disease.
autoimmune disease (34 papers, 2010 to 2025). A disorder resulting from loss of function or tissue destruction of an organ or multiple organs, arising from humoral or cellular immune responses of the individual to their own tissue constituents. "This form is usually associated with autoimmune disease, paraneoplastic syndromes, medications such as ACE inhibitors or changes in estrogen levels." (PMID 21320328, 2011). "Some other SNPs, such as A5466C, T3892C, A240T, C1237T, G2215A, A2350G, and C3409T, of ACE gene may affect the risk of certain autoimmune diseases including IgA nephropathy and lupus nephropathy." (PMID 33117150, 2020). "The role of ACE polymorphism has been investigated as a risk factor for several diseases such as inflammatory and immune-related disorders, particularly the rheumatic and autoimmune diseases." (PMID 30765613, 2019). "In previous studies, ACE gene was found associated with rheumatic and autoimmune diseases." (PMID 30765613, 2019). "As the ACE gene has different SNP sites, and research studies have shown that SNPs are capable of changing the structure of the genome and influence protein expression and function that leads to increased risk of different autoimmune diseases, for e.g., SLE." (PMID 30618805, 2018). "ACE has a significant role in the physiology of the blood vessels and inflammatory process and it has been widely studied to detect its association with various autoimmune diseases." (PMID 26177100, 2015). "Previous investigations have shown that elevated levels of ACE have been associated with autoimmune diseases and an I/D polymorphism of the ACE gene accounts for most of the variability of serum ACE activity, with DD and II genotypes having the highest and the lowest activity, respectively." (PMID 26177100, 2015). "The cause of AE was identified in 59 (37%) cases: 3 (2%) patients had a low plasma C1-INH and C4 levels; 20 (12%) were ACE inhibitor-induced;12 (7%) were associated with autoimmune disorders; 7 (4%) were associated with malignancy; and 17 (11%) were related to use of NSAIDs." (PMID 25670937, 2014). "Six SNPs (A-5466C, T-3892C, A-240T, C1237T, G2215A and A2350G) of the ACE gene and two SNPs (T-786C and G894T) of the eNOS gene have been selected since they may affect the susceptibility to some autoimmune diseases." (PMID 20540812, 2010). "Recent studies have reported that several SNPs (A-5466C, T-3892C, A-240T, CJ237T, G2215A and A2350G) of the ACE gene may affect the risk of certain autoimmune diseases such as essential hypertension, left ventricular hypertrophy, IgA nephropathy, diabetic nephropathy and so on." (PMID 20540812, 2010). "ACE inhibitors in immunity are usually studied in the context of autoimmune disorders, often regarding a beneficial patient outcome, but with a lack of research on the cellular uptake of ACEi, or which processes are impacted." (PMID 36016727, 2022). "In contrast, ACE is also elevated in certain autoimmune diseases such as rheumatoid arthritis and lupus, and its inhibition benefits patient outcome where inflammatory immune cells are overactive." (PMID 36016727, 2022). "A further objective was to classify patients according to etiology: decreased levels of C1-INH and C4, ACE inhibitor-induced, autoimmune disease, malignancy, NSAID-induced, or idiopathic." (PMID 25670937, 2014). "In conclusion, ACE reduced urine protein and creatinine levels and suppressed the thickening of the kidney glomerular basement membrane, suggesting that ACE protects the kidney from immunological damage resulting from autoimmune disease." (PMID 18955361, 2011). "As new data arise, revisions might soon be needed allowing AIT in the cases of patients treated with ACE inhibitors and beta-blockers, in elderly patients and in patients with concomitant autoimmune diseases and neoplasias in remission." (PMID 31528333, 2019).
autoimmune disease (continued). "In conclusion, ACE reduced urine protein and creatinine levels and caused a reduction in the kidney glomerular basement membrane thickness, suggesting that ACE is able to protect the kidneys from the immunological damage characteristic of this autoimmune disease." (PMID 18955361, 2011). "Thus, ACE may also serve as a useful target for the treatment of inflammatory conditions or autoimmune diseases since all immune cells express local RAAS components." (PMID 36016727, 2022). "Patients were categorized according to the proposed pathogenesis of AE: low C1 inhibitor (C1-INH) and C4 levels, autoimmune disease, cancer, angiotensin-converting enzyme (ACE) inhibitor-induced, nonsteroidal antiinflammatory drug (NSAID)-induced, or idiopathic." (PMID 25670937, 2014).
sarcopenia (34 papers, 2011 to 2026). Progressive decline in muscle mass due to aging which results in decreased functional capacity of muscles. "As with sarcopenia, the role of the ACE I/D variant as a risk factor for AD is somewhat opaque, but a recent meta-analysis, using data from 65 studies, found some evidence to suggest that the I allele increased risk." (PMID 38790190, 2024). "Of note, the results of this study indicated that TRIM63, a crucial regulator of sarcopenia, is linked to skeletal muscle atrophy but also to the pathological process of IDD by regulating ACE ubiquitination degradation." (PMID 40520007, 2025). "ACE inhibitors have been shown to decrease the chances of developing sarcopenia by blocking the production of AngII." (PMID 39409095, 2024). "In current studies, ACE inhibitors significantly improved muscle mass and function in 70-year-old patients with sarcopenia." (PMID 39409095, 2024). "In this study therefore, we analysed the genotypes of individuals with sarcopenia, enrolled into the LACE study to determine any association of ACE genotype with strength or muscle mass." (PMID 37862321, 2023). "ACE inhibitors block the production of AngII and potentially inhibit the development of sarcopenia by inhibiting AngII mediated muscle atrophy." (PMID 34553120, 2021). "Pharmacological therapies for sarcopenia (testosterone, androgen receptor modulators, ghrelin agonists, myostatin inhibitors, ACE inhibitors) have been evaluated, but they are generally less effective than postulated (idem)." (PMID 33327483, 2020). "Leucine and ACE inhibitors in sarcopenia (LACE) is a multicentre, masked, placebo-controlled, 2 × 2 factorial randomised trial evaluating the efficacy of leucine and perindopril (angiotensin converting enzyme inhibitor (ACEi)) in patients with sarcopenia." (PMID 29301558, 2018). "Pharmacological inhibition seems to protect humans and mice from sarcopenia, but further studies are needed to better define the function of ACE during sarcopenia." (PMID 24092876, 2013). "Further evidence is required before recommending ACE inhibitors to counter the effects of sarcopenia." (PMID 22500226, 2012). "Angiotensin converting enzyme (ACE) inhibitors and angiotensin II receptor blockers (ARBs) are two classes of drugs used to mediate this pathway and both classes have been studied in sarcopenia." (PMID 22184279, 2011). "However, in the present study, ACE inhibitors/ARBs (53%), beta-blockers (38%), and MRAs (26%) were used insufficiently at discharge, particularly in patients with HFrEF and sarcopenia (55%, 38%, and 34%, respectively)." (PMID 38683441, 2024). "It is therefore difficult to predict the effect of ACE genotype on the likelihood of sarcopenia as DD individuals may have started with a larger muscle mass and greater strength with a higher type II fibre composition that is more susceptible to loss." (PMID 37862321, 2023). "Taking ACE inhibitors may support muscle metabolism and physical therapy for older people with more severe sarcopenia." (PMID 34205250, 2021). "From that point of view, sarcopenia may be a potential curative choice for angiotensin-converting enzyme (ACE) inhibitors that are widely used in the geriatric population." (PMID 33920130, 2021). "Pharmacological therapies for sarcopenia including inhibitors of myostatin, testosterone, selected androgen receptor modulators, ghrelin agonists, and angiotensin-converting enzyme (ACE) inhibitors have been evaluated, but preliminary trials have found that they are less effective than postulated." (PMID 27800156, 2016). "The LACE clinical trial was designed to determine whether ACE inhibition would reduce further muscle loss in individuals with sarcopenia but suffered from low recruitment and returned a negative result." (PMID 37862321, 2023). "ACE inhibitors can increase mitochondrial numbers and IGF-I levels thereby helping to counter sarcopenia." (PMID 22500226, 2012).
sarcopenia (continued). "We recently conducted and published a multicentre 2 x 2 factorial RCT of leucine and ACE inhibitors in older people with sarcopenia (the LACE trial) which also showed no overall benefit from perindopril (an ACEi) therapy." (PMID 37862321, 2023). "Many clinical trials have investigated the use of ACE inhibitors as treatment against sarcopenia with non-uniform functional results; some reports show improvement while others show no change." (PMID 22184279, 2011). "However, PWH using AT1R blockers, but not those how use ACE inhibitors, exhibited increased lower limb strength and physical function, lower prevalence of sarcopenia, and decreased oxidative stress." (PMID 40421794, 2025). "In conclusion, our results demonstrated that AT1R blockage, but not ACE inhibitors, may protect PWH against muscle wasting, strength loss, and sarcopenia." (PMID 40421794, 2025). "Thus, although overactivity of skeletal myocyte KATP channels might contribute to atrophy, ACE/Ang II/ATR1 signaling is also a known mediator of atrophy and sarcopenia in skeletal muscle and a potential major driver of the muscle pathology." (PMID 34359961, 2021). "Although current evidence does not support further trials of ACE inhibitors as standalone or adjuncts to exercise for people with sarcopenia, further trials are needed to test whether leucine could benefit patient subgroups with low muscle mass and/or low protein intake." (PMID 35174663, 2022).
Hypokalemia (33 papers, 2009 to 2026). An abnormally decreased potassium concentration in the blood. "It has been reported that phenylephrine, angiotensin II infusion and hypokalemia induce the ACE expression, which has been associated with kidney hypoxia and damage." (PMID 30618804, 2018). "The cellular mechanisms underlying the effects of hypokalemia on ACE expression are unclear." (PMID 32625100, 2020). "ACE inhibitors, aldosterone receptor blockers, and beta blockers could potentially prevent hypokalemia by opposing the neurohumoral activation associated with HF that lowers serum-[K+]." (PMID 30464746, 2018). "Furthermore, hypokalaemia causes alterations in the levels of vasoactive mediators: an increase in vasoconstrictor stimuli (ACE, ET-1 and subtype B α-adrenergic receptors) and a reduction in vasodilatory stimuli (EDRF-1 and PGE2)." (PMID 19144110, 2009). "The combination of ACE inhibitors or angiotensin-receptor blockers with thiazide diuretics might also help in the maintenance of potassium homeostasis and reduce the risk of hyper- or hypokalemia." (PMID 38263021, 2024). "It was demonstrated in rats, that hypokalemia maintained for 12 weeks increases the expression of cortical ACE and endothelin-1." (PMID 32625100, 2020). "It was also notable that hypokalaemia was seen despite the frequency of concurrent therapy with ACE inhibitors, AT1 receptor antagonists and potassium supplements." (PMID 25139696, 2015). "These drugs reduce blood pressure via different mechanisms and may also induce various adverse reactions, such as dry cough with ACE inhibitors, ankle edema with CCBs, and hypokalemia with thiazide diuretics." (PMID 38263021, 2024). "It is already established that LDs might interact with several medications including digoxin, amphotericin B, angiotensin-converting enzyme inhibitors (ACE inhibitors), antifungal agents, antidiabetic drugs, dobutamine, and sotalol due to diuretic-associated hypokalemia." (PMID 40757528, 2023). "Two of the most prominent reasons for low lymphocytes are hypokalemia (low potassium levels) and hypophosphatemia (low sodium levels), induced due to the impact of SARS-CoV-2 on patients ACE-Angiotensin-II (ACE-Ang-II) that prevents the degradation of intact Ang-II within the system." (PMID 34595136, 2021). "The prevalence was more likely to be higher in patient populations that were studied before the introduction of beta-blockers, ACE-inhibitors, and AT1-antagonists as standard HF therapy, as all of these drugs increase serum K+ levels and thus counteract hypokalemia." (PMID 30464746, 2018).
cerebrovascular disease (32 papers, 2009 to 2025). "ACE (angiotensin-converting enzyme) is the main candidate gene for genetic susceptibility to cardiovascular and cerebrovascular diseases." (PMID 33505489, 2021). "As exposure to higher plasma ACE concentrations may result in vascular wall thickness and stiffness, higher plasma ACE concentrations are associated with the risk of cardiovascular and cerebrovascular disease." (PMID 26710338, 2015). "Several B. subtilis, B. amyloliquefaciens, and B. velezensis had anti-cerebrovascular disease activity, including increasing fibrinolytic, antioxidant, and ACE inhibitory activity." (PMID 34835364, 2021). "The specific strains of B. subtilis and B. velezensis had antioxidant, fibrinolytic, and ACE inhibitory activity, and they can be used as a starter culture to produce better quality controlled Kochujang with anti-cerebrovascular disease activities." (PMID 34835364, 2021). "Growing evidence implicates angiotensin–converting enzyme (ACE), a key enzyme of the rennin-angiotensin system, as an important modulator of cerebrovascular disease (CVD)." (PMID 23826288, 2013). "In the multivariable logistic regression model, age, Killip classification, CKD, cerebrovascular disease, use of ß-blocker, ACE inhibitor/ARB, statin, Hb, HDL cholesterol, preprocedural suboptimal flow (TIMI 0 or 1 flow) and LVEF were independent predictors of overall mortality." (PMID 31199840, 2019). "In the PROGRESS study that enrolled patients with history of cerebrovascular disease, there were no ACE-genotype specific benefits of perindopril administration on the outcome of fatal CAD and nonfatal MI." (PMID 19497121, 2009).
acute coronary syndrome (31 papers, 2004 to 2025). Signs and symptoms related to acute ischemia of the myocardium secondary to coronary artery disease. "The study comparing the distribution of ACE genotypes in Korean patients suffering from acute coronary syndrome and in healthy subjects indicated that the genotype DD of the ACE gene may be an independent risk factor of acute coronary syndrome." (PMID 38279313, 2024). "For the secondary prevention of acute coronary syndrome, clinical guidelines recommend all 4 therapies (antiplatelets, beta-blockers, ACE inhibitors/ARB, and statins) for long-term use for a major benefit." (PMID 35694663, 2022). "In patients with acute coronary syndrome, pre-admission treatment with statins, beta blockers or ACE inhibitors reduced MPO levels." (PMID 26280875, 2016). "Active management should involve assessing for acute coronary syndrome as an alternative diagnosis and initiating acute heart failure treatment, including ACE inhibitors or angiotensin receptor blockers, beta-blockers, and diuretics to reduce ventricular filling pressures." (PMID 40746649, 2025). "A systematic review and meta-analysis of 28 studies involving patients with acute coronary syndromes found that women were less adherent to lipid-lowering therapies, whereas no significant gender differences were reported for antiplatelet agents or ACE inhibitors." (PMID 40951135, 2025). "In patients with acute coronary syndrome (ACS), angiotensin-converting enzyme (ACE) inhibitors are preferred over angiotensin receptor blockers (ARBs)." (PMID 33337519, 2021). "In a multinational, multicentre trial of individuals with acute coronary syndromes (ACS), 1999–2003, discontinuation rates at six months were 8% for aspirin, 13% for statins, 20% for ACE inhibitors." (PMID 29522561, 2018). "In the case of patients with acute coronary syndrome (ACS), international guidelines recommend the combined use of antiplatelets, beta-blockers, angiotensin-converting enzyme (ACE) inhibitors/angiotensin II receptor blockers (ARB), and statins for the secondary prevention of this condition." (PMID 35694663, 2022).